ICOS (inducible T cell costimulator)
Diseases named in the same sentence as ICOS in open-access papers (continued):
Sharing a sentence is not in itself a finding about the gene and the disease.
skin disorder (1 paper, 2025). Any deviation from the normal structure or function of the skin or subcutaneous tissue that is manifested by a characteristic set of symptoms and signs. "In conclusion, the insight from our study into the relevance of ICOS+CD4+ T cells is potentially meaningful for a better understanding of irAE pathogenesis beyond lung toxicity, including skin disorders." (PMID 40198121, 2025).
ICOS also shares sentences with these, for which no sentence is quoted: multiple sclerosis (6 papers); Allergy (4); esophageal cancer (4); acute myeloid leukemia (3); autoimmune thyroid disease (3); celiac disease (3); Löfgren’s syndrome (3); lung adenocarcinoma (3); myocarditis (3); atopic dermatitis (2); breast invasive carcinoma (2); lupus nephritis (2); lymphopenia (2); MALT lymphoma (2); Miscarriage (2); stomach adenocarcinoma (2); Stroke (2); thyroid cancer (2); ulcerative colitis (2); Alzheimer disease (1); autoimmune lymphoproliferative syndrome (1); autoimmune uveitis (1); Beckwith-Wiedemann syndrome (1); Behçet’s disease (1); Blau syndrome (1); cardiomyopathy (1); cerebral cyst (1); chronic rhinosinusitis (1); colorectal tumors (1); coronary heart disease (1).
A further 54 diseases each share a sentence with ICOS in 1 paper.